GABBR2 (gamma-aminobutyric acid type B receptor subunit 2)
Diseases named in the same sentence as GABBR2 in open-access papers (continued):
Sharing a sentence is not in itself a finding about the gene and the disease.
bipolar disorder (2 papers, 2020 to 2024). A disorder of the brain that causes unusual shifts in mood, energy, activity levels and the ability to carry out day-to-day tasks. "GABBR2 is also associated with bipolar disorder and dementia." (PMID 39228919, 2024). "Reductions in GABBR1 and GABBR2 proteins are observed in prefrontal cortex of subjects with bipolar disorder." (PMID 33006978, 2020). "Additionally, a post-mortem study revealed reduced protein expressions of GABBR1 and GABBR2 in the cerebellum of patients with bipolar disorder." (PMID 39228919, 2024). "In conclusion, CACNA1C, GABBR2, SCN2A, CTSH, MSRA, and SH3PXD2A may be associated with the neuro-progression of bipolar disorder to dementia." (PMID 39228919, 2024). "In conclusion, the genes CACNA1C, GABBR2, SCN2A, CTSH, MSRA, and SH3PXD2A may be associated with the neuro-progression of bipolar disorder to dementia." (PMID 39228919, 2024). "According to GWAS, the CACNA1C, GABBR2, SCN2A, CTSH, MSRA, and SH3PXD2A genes were common between bipolar disorder and dementia." (PMID 39228919, 2024). "The results showed that the genes CACNA1C, GABBR2, SCN2A, CTSH, MSRA, and SH3PXD2A were overlapping between patients with bipolar disorder and dementia." (PMID 39228919, 2024).
cholangiocarcinoma (2 papers, 2023 to 2025). A carcinoma that arises from the intrahepatic biliary tree (intrahepatic cholangiocarcinoma) or from the junction, or adjacent to the junction, of the right and left hepatic ducts (hilar cholangiocarcinoma). "In cholangiocarcinoma specimens, high GABBR2 expression was strongly associated with more aggressive nonpapillary histology yet small tumor size." (PMID 37762034, 2023).
dementia (2 papers, 2022 to 2024). Loss of intellectual abilities interfering with an individual's social and occupational functions. "Rare variants in the GABBR2 gene therefore might only affect nonclinical variation of synaptic functioning, without consequences on neurodegeneration or dementia symptoms." (PMID 35173266, 2022).
developmental and epileptic encephalopathy (2 papers, 2024 to 2025). An epilepsy associated with developmental impairment that may be due to either the underlying etiology or the superimposed epileptic activity, or both. "Within the cohort of patients experiencing developmental and epileptic encephalopathy (DEE), WES has revealed genetic variants in novel genes (FGF12, GABBR1, GABBR2, ITPA, KAT6A, PTPN23, RHOBTB2, SATB2) and candidate epilepsy-associated genes (CAMTA1, FAT3, GABRA6, HUWE1, PTCHD1)." (PMID 39523358, 2024).
Insulin resistance (2 papers, 2019 to 2025). Increased resistance towards insulin, that is, diminished effectiveness of insulin in reducing blood glucose levels. "For example, maternal Omega-3 PUFA intake during pregnancy affects offspring DNA methylation, influencing genes like MSTN, IFNA13, ATP8B3, and GABBR2, which are linked to insulin resistance, adiposity, and immune responses." (PMID 40507105, 2025). "Genes such as MSTN, IFNA13, ATP8B3, and GABBR2 showed methylation changes, potentially influencing insulin resistance, adiposity, and innate immune response in offspring." (PMID 40507105, 2025).
ischemia (2 papers, 2021 to 2025). A hypoperfusion of the BLOOD through an organ or tissue caused by a PATHOLOGIC CONSTRICTION or obstruction of its BLOOD VESSELS, or an absence of BLOOD CIRCULATION. "Overall, these evidences demonstrated that GABBR2 is an important regulator in promoting angiogenesis post-ischemia." (PMID 34422926, 2021). "Our present results illustrated that GABBR2 knockdown inhibited the angiogenesis process post-ischemia by regulation of the glycolysis-dominant metabolism." (PMID 34422926, 2021). "In addition to its role in neurons, endothelial GABBR2 promoted angiogenesis by regulating the glycolysis pathway in post-ischemia model." (PMID 40927314, 2025). "The results also showed a markedly upregulated expression of GABBR2 in hindlimb post-ischemia." (PMID 34422926, 2021). "Our present study indicated that GABBR2 might be a potential therapeutic target in modulating EC metabolism and the process of ischemia in PADs." (PMID 34422926, 2021).
lung carcinoma (2 papers, 2013 to 2022). "Furthermore, our clinical data analysis showed that both GABAA receptors (GABRA3) and GABAB receptor (GABBR2) genes were significantly expressed in the early pathological stage (stage I and II) of the lung cancer patients, and the expression was gone in stage III and IV." (PMID 23617850, 2013).
nicotine dependence (2 papers, 2009 to 2010). Physical and psychological dependence on nicotine. "NRXN3 and GABBR2 were identified using this approach and also in linkage studies of opiate dependence and association studies of nicotine dependence, for example." (PMID 20098672, 2010).
non-small cell lung carcinoma (2 papers, 2022 to 2023). A group of at least three distinct histological types of lung cancer, including non-small cell squamous cell carcinoma, adenocarcinoma, and large cell carcinoma. "Nonetheless, the elevated expression of GABBR2 has been reported in several types of neoplasm such as thyroid adenoma and carcinoma and non-small cell lung cancer." (PMID 37762034, 2023). "Furthermore, GABBR2 level increased in non-small cell lung cancer, and patients with high expression of GABBR2 showed better prognosis." (PMID 36059697, 2022).
papillary thyroid cancer (2 papers, 2018 to 2022). "Similarly, Schulten and colleagues reported that GABBR2 was one of the most significantly upregulated genes in the follicular variant of papillary thyroid carcinoma." (PMID 36059697, 2022). "In radiation-induced papillary thyroid cancer from chernobyl pediatric patients, GABBR2 was highly expressed, and related to tumor occurrence." (PMID 29740512, 2018).
vascular dementia (2 papers, 2024 to 2025). A degenerative vascular disorder affecting the brain. "Given the clinical overlap between vascular dementia (VaD) and AD, GABBR2 expression was specifically evaluated in VaD." (PMID 40927314, 2025).
bladder cancer (1 paper, 2023). "When excluding those with noninvasive tumor who had been much less likely to die of bladder cancer, high GABBR2 expression was still associated with a significantly higher mortality rate." (PMID 37762034, 2023). "Similarly, using a publicly available database, we here found that those with invasive bladder cancer showing high GABBR2 expression had a significantly higher risk of overall mortality." (PMID 37762034, 2023). "In the present study, we further investigated the functional role of GABBR2 in CDDP resistance in bladder cancer in relation to AR signaling." (PMID 37762034, 2023). "We then found that knockdown of GABBR2 via its shRNA or its inactivation via a GABA B receptor antagonist enhanced the cytotoxic effects of CDDP in AR-positive bladder cancer cells." (PMID 37762034, 2023). "Based on the findings in DNA microarray analysis in control AR-positive vs. AR-knockdown bladder cancer sublines we had previously performed, we anticipated that GABBR2 functioned as a downstream target of AR." (PMID 37762034, 2023). "Using its inhibitor and knockdown, we assessed the impact of GABBR2 on the growth of bladder cancer cells." (PMID 37762034, 2023). "Specifically, androgen treatment and AR knockdown/antiandrogen treatment induced and reduced, respectively, the levels of GABBR2 expression in bladder cancer cells." (PMID 37762034, 2023). "We identified GABBR2 as a key downstream effector of AR in modulating CDDP sensitivity in bladder cancer." (PMID 37762034, 2023). "A chromatin immunoprecipitation assay further revealed the binding of AR to the promoter region of GABBR2 in bladder cancer cells." (PMID 37762034, 2023). "We first demonstrated that AR directly regulated the expression of GABBR2 via binding to its promoter in bladder cancer cells." (PMID 37762034, 2023). "Accordingly, inhibition of GABBR2 has the potential of being a means of chemosensitization, especially in patients with AR/GABBR2-positive bladder cancer." (PMID 37762034, 2023). "Meanwhile, GABBR2 expression was significantly elevated in a cisplatin-resistant bladder cancer subline, compared with control cells." (PMID 37762034, 2023). "Our DNA microarray analysis in control vs. AR-knockdown bladder cancer sublines suggested that the expression of a GABA B receptor GABBR2 and AR was correlated." (PMID 37762034, 2023). "In AR-positive bladder cancer cells, knockdown of GABBR2 or treatment with a selective GABA B receptor antagonist, CGP46381, considerably enhanced the cytotoxic activity of cisplatin." (PMID 37762034, 2023). "A publicly available database was searched for analyzing the prognostic significance of GABBR2 expression in bladder cancer." (PMID 37762034, 2023). "The present study aimed to determine the functional role of GABBR2 in modulating cisplatin sensitivity in bladder cancer." (PMID 37762034, 2023). "Thus, GABBR2 expression was correlated with the expression and activity of AR in bladder cancer cells." (PMID 37762034, 2023). "We then found that GABBR2 was involved in promoting CDDP resistance in bladder cancer cells." (PMID 37762034, 2023). "We then determined if GABBR2 could modulate sensitivity to CDDP treatment in bladder cancer cells." (PMID 37762034, 2023). "Nonetheless, CGP46381 treatment in three AR-positive bladder cancer cell lines, as well as GABBR2 knockdown in UMUC3 cells, did not significantly change their proliferation (via MTT assay) or migration (via wound-healing assay)." (PMID 37762034, 2023). "The present study aimed to explore whether gamma-aminobutyric acid (GABA) B receptor 2 (GABBR2), which belongs to the G protein-coupled receptor superfamily, functions as a downstream effector of AR and induces resistance to CDDP therapy in bladder cancer." (PMID 37762034, 2023). "However, GABBR2 did not appear to affect bladder cancer cell proliferation and migration in the absence of CDDP." (PMID 37762034, 2023).
bladder tumor (1 paper, 2023). "Our data suggest that not only concurrent antiandrogen therapy but also GABBR2 inhibitor treatment has the potential of being a means of chemosensitization, especially in patients with AR/GABBR2-positive bladder tumor." (PMID 37762034, 2023).
bone fracture (1 paper, 2020). "Furthermore, we discovered that two genes coding for the GABA receptors GABBR2 and GLRA1 and the gene coding for glutamate decarboxylase GAD1, showed an association with total body BMD, and remarkably GABBR2 associated with bone fractures." (PMID 31969651, 2020).
cervical dystonia (1 paper, 2021). "For example, SNPs in COL8A1, DENND1A, and GABBR2 were found to be associated with cervical dystonia in a multicenter GWAS." (PMID 35273550, 2021).
cocaine addicts (1 paper, 2013). "Factor 2: genes involved in synaptic transport: with the exception of GABBR2 that loads more strongly on factor 1, the remaining six genes all showed altered expression in alcoholics/cocaine addicts." (PMID 23717525, 2013).
Fever (1 paper, 2024). Body temperature elevated above the normal range. "Low RMSD, RMSF, Rg, and SASA values as well as high intermolecular interactions indicated that GABBR2–saikosaponin C, GABBR2–baicalin, NFKBIA–glycyrrhizic acid, and PTGS2–lobetyolin complexes were quite stable, highlighting their potential as promising candidates for fever treatment." (PMID 38675434, 2024).
lung adenocarcinoma (1 paper, 2020). A carcinoma that arises from the lung and is characterized by the presence of malignant glandular epithelial cells. "This locus has neither been reported in the GWAS of UF or OC, however, GABBR2 is suggested to have an important role in EGFR signaling through the ERK1/2 pathway, as reported in lung adenocarcinoma." (PMID 31488892, 2020).
Neurodevelopmental delay (1 paper, 2021). "Except for one truncating variant described in a large sequencing study on patients with neurodevelopmental delay, all GABBR2 pathogenic variants described until now in this gene are missense (source: HGMD Professional, release 2020.2, see Web Resources)." (PMID 33941880, 2021).
ovarian carcinoma (1 paper, 2024). A malignant neoplasm originating from the surface ovarian epithelium. "The gamma-aminobutyric acid type B receptor subunit 2 (GABBR2) locus was discovered to pertain to combined phenotypes of UL and ovarian cancer, while the SH3 domain containing the GRB2-like 3/basonuclin zinc finger protein 1 (SH3GL3/BNC1) locus was associated solely with UL." (PMID 38790186, 2024).
Parkinson’s (1 paper, 2017). "Some of the genes that were steadily down-regulated, such as Pink1, Park 2, Sv2b, Gabbr2, Sept5 and Atxn2, were directly related to Parkinson’s onset." (PMID 29156651, 2017).
substance dependence (1 paper, 2023). The psychological or physiological need to take a substance in order to experience its effects or to avoid the effects of its absence. "These included genes conferring heritable risk for nicotine and other substance dependence, such as GABBR2 encoding a GABAB receptor, and SHC3 involved in MAP kinase and neurotrophin signaling." (PMID 37699936, 2023).
type 2 diabetes (1 paper, 2013). "The GMDR has been successful in identifying the significant interaction of CHRNA4 with CHRNB2, NTRK2 with BDNF, and GABBR1 with GABBR2 in nicotine dependence, of LEPR and ADRB2 in obesity, and of HNF4A and KCNJ11 in type 2 diabetes (T2D)." (PMID 23626757, 2013).
tumor (16 papers, 2013 to 2025). "Data obtained from GSE32894 showed that the rate of overall survival was significantly lower in the entire cohort of patients with high GABBR2 tumor." (PMID 37762034, 2023). "The results showed that both GABARAP and GABBR2 were highly expressed in the tumor tissues, and the fold change of GABBR2 was more significant." (PMID 38105184, 2023). "100% and 69% of ACC tumor samples expressed transcripts encoding GABBR1 and GABBR2, with upregulation in 8% and 15% of patients, respectively." (PMID 33187258, 2020). "Modulation of GABBR2 could potentially affect tumour progression by altering these signalling pathways." (PMID 39915814, 2025). "Our results indicated that the expression levels of an array of classic and putative tumor suppressor genes, such as P63, Fasl, Gabbr2, and Gzma (granzyme A), were extensively diminished in mouse transplanted tumors following heat-killed P. intermedia treatment." (PMID 38515216, 2024). "Among them, GABBR2 and TUFT1 exhibited high expression levels in tumor tissues, whereas SPEF2 demonstrated low expression." (PMID 41217541, 2025). "The low-risk miRNAs from has-let-7 family (hsa-let-7c, hsa-let-7b) act as tumour suppressors through controlling cellular processes such as cell projection, cell proliferation, and cell development, involving the genes KRT5 and GABBR2." (PMID 32182819, 2020). "There are clear expression differences between clinicogeneticsubgroups, consistent both with the ANOVA analysis of CIS gene expression acrosssubgroups and with the presence of genespreviously shown to be highly expressed in Group 3 and 4 tumours (e.g.NEUROD2, GABBR2)." (PMID 24252690, 2013). "Data suggest that the activation of GABBR2 plays an important role in suppressing the proliferation and migration of various human tumor cells and in the inactivation of cAMP-responsive element binding protein (CREB) and extracellular regulated kinase (ERK) in tumor cells." (PMID 34316327, 2021).
cancer (8 papers, 2013 to 2025). A tumor composed of atypical neoplastic, often pleomorphic cells that invade other tissues. "GABBR2 has been implicated in promoting cancer cell proliferation and invasion by interacting with other signalling pathways, such as the Wnt/β-catenin pathway." (PMID 39915814, 2025). "miR-31-3p directly targets GABBR2, indicating that miR-31-3p exerts anti-cancer effects via regulation of GABBR2 expression." (PMID 36059697, 2022). "hsa-miR-342-3p was negatively correlated with downregulated gene targets such as ZNF462 and NCOA7, and hsa-let-7b/c were anti-correlated with predicted targets KRT5 and GABBR2, with known activities in the cancer pathways." (PMID 32182819, 2020). "We also discovered 22 riboSNitch-depleted 3′UTRs, but only two of them (KPNA4 and GABBR2) were identified as cancer-specific." (PMID 31160636, 2019). "Stein and colleagues first reported the possible role of GABBR2 in cancer progression." (PMID 36059697, 2022). "However, as the role of GABBR2 in cancer remains unclear, additional mechanisms by which miR-31-3p inhibits cancer growth following GABBR2 overexpression should be further investigated." (PMID 36059697, 2022). "Although the role of GABBR2 in cancer is not yet understood, several reports have revealed its aberrant expression in cancer." (PMID 36059697, 2022). "Interestingly, in several nonurothelial cancer cells, cooperation of GABBR2 with EGFR-ERK1/2 signaling has been documented, while the ERK1/2 pathway has been linked to CDDP resistance." (PMID 37762034, 2023).
psychiatric disorder (6 papers, 2014 to 2025). A disorder characterized by behavioral and/or psychological abnormalities, often accompanied by physical symptoms. "Advances in high-throughput genomic technologies, particularly whole-exome sequencing, have uncovered hundreds of variants in the genes encoding the GBR subunits, GABBR1 and GABBR2, many of which are linked to neurological and psychiatric disorders." (PMID 40756990, 2025).
neurodevelopmental disorder (4 papers, 2018 to 2026). A behavioral and cognitive disorder with onset during the developmental period that involves impaired or aberrant development of intellectual, motor, or social functions. "Monoallelic de novo missense variants in GABBR1 and GABBR2, which encode the receptor subunits, have been associated with neurodevelopmental disorders." (PMID 41803176, 2026).
GABBR2 also shares sentences with these, for which no sentence is quoted: infection (9 papers); AIDS (3); Fabry disease (3); attention deficit-hyperactivity disorder (2); brain diseases (2); CMV infection (2); CMV retinitis (2); developmental delay (2); Huntington disease (2); malignant melanoma (2); retinitis (2); Rett syndrome (2); anterior uveitis (1); anxiety disorder (1); breast tumors (1); cardiac hypertrophy (1); chronic gastritis (1); cognitive decline (1); colorectal cancer (1); Erythema (1); gastric adenoma (1); gastric carcinoma (1); gastric tumors (1); genital herpes (1); glial tumors (1); infectious disease (1); late-onset Alzheimers disease (1); latent infection (1); mastitis (1); memory impairment (1).
A further 12 diseases each share a sentence with GABBR2 in 1 paper.